BOK (BCL2 family apoptosis regulator BOK)
Diseases named in the same sentence as BOK in open-access papers (continued):
Sharing a sentence is not in itself a finding about the gene and the disease.
cancer (21 papers, 2017 to 2025). A tumor composed of atypical neoplastic, often pleomorphic cells that invade other tissues. "Fifty-six genes were identified as significant genes and included cancer-associated genes such as BOK, FANCD2, ADRM1 and EGLN1." (PMID 32437477, 2020). "More recently, in a chemical (DEN)-induced model of liver carcinogenesis, loss of BOK has been shown to protect against cancer." (PMID 29769323, 2018). "Alternative splicing as a mechanism can produce BOK transcript variants that might contribute to its diverse functions in cancer." (PMID 37888203, 2023). "It seems pertinent loss of Bok is a relatively frequent event in a range of cancers and gene silencing may result in loss of BOK protein in additional cases." (PMID 29769323, 2018). "Cancer cells that stably express BOK rely to a significant extent on this effector protein for the execution of apoptosis in response to select cytotoxic drugs." (PMID 39996719, 2025). "Knowing that BOK is frequently deleted in cancers, while BCL-B is often amplified, we next aimed to identify cell lines with detectable endogenous levels of both proteins." (PMID 39996719, 2025). "Although the role of BOK remains controversial, the mechanisms by which it regulates cancer cell invasion and migration are unclear." (PMID 40806384, 2025). "Recent studies point towards a wide complexity of BOK in cancer, which can be attributed to the variety of alternative transcripts of this gene." (PMID 37888203, 2023). "This literature evidence confirms that the BOK gene is involved in apoptosis, cancer, and inflammation in the colon, which can serve as a diagnostic marker gene in CD patients." (PMID 37994325, 2023). "Of note, compared with other proapoptotic BCL-2 family members, BOK levels are often reduced in cancer by various means, and there is increasing evidence for BOK modulating tumorigenesis." (PMID 33043006, 2020). "Despite these promising findings, further work will be necessary for the future to establish BOK as a prognosis marker in cancer." (PMID 33291826, 2020). "Unexpectedly, among the pro-apoptotic family members, BOK is one of the most frequently deleted genes in cancer cells." (PMID 33291826, 2020). "The tumor suppressor function of BOK was first proposed based on the finding that the genomic locus containing the BOK gene was frequently deleted in different human cancers." (PMID 33291826, 2020). "In particular, genes known to be associated with cancer such as LAMC2, UBE2C, AKT2, AKT2, BOK, MAP4, and FANCD2 were noted to be aberrantly spliced, indicating that the aberrant expression of CPSF1 significantly altered the ASEs of oncogenes in each dataset." (PMID 32437477, 2020). "Of the BAX/BAK-like BCL-2 protein subfamily, the role of BOK is just recently being explored in the context of human cancers." (PMID 29374142, 2018). "Despite its critical role in apoptosis, the regulation of BOK expression is poorly understood in cancers." (PMID 29156771, 2017). "Being frequently deleted in cancers, BOK has been identified as a tumor-suppressor." (PMID 39996719, 2025). "Additionally, a previous study provided evidence for the potential role of BOK as a tumor suppressor in cancer and considered that the BOK gene was silenced in many human cancers." (PMID 40806384, 2025). "For instance, BOK is frequently deleted in cancers while MCL-1 is often amplified." (PMID 39996719, 2025). "Notably, our research reveals that these novel BOK circRNAs exhibit cell line-specific expression profiles, with some circRNAs being unique to particular cancer cell lines." (PMID 37888203, 2023). "BOK has been shown to be genomically deleted across several cancer entities." (PMID 35091677, 2022). "What is its role in cancer progression, and why do many types of human cancer lose BOK expression?" (PMID 33043006, 2020). "In a variety of human cancers, BOK is frequently found to be downregulated." (PMID 33043006, 2020).
cancer (continued). "Interestingly, the genomic region containing BOK was identified to be relatively frequently deleted across many types of human cancers." (PMID 33043006, 2020). "There is increasing evidence pointing toward BOK as a prognostic or predictive marker in cancer." (PMID 33043006, 2020). "However, the role of BOK in cancer cell death is still controversial and its role as a prognostic biomarker in CRC has not yet been explored." (PMID 29374142, 2018). "A somatic copy-number alterations study investigating 3131 cancer specimens suggested that BOK may act as a tumour suppressor across several human cancers." (PMID 29374142, 2018). "Taken together, our results suggest that fine tuning of the levels of pro-apoptotic protein BOK and anti-apoptotic protein Mcl-1 may decide the fate of cancer cells to either undergo apoptosis or proliferation." (PMID 29156771, 2017). "Therefore, understanding the role of BOK in cancer is crucial." (PMID 40806384, 2025). "Therefore, it is likely that GSK3α/β-dependent phosphorylation of BOK may be one of the important mechanisms that control BOK expression and function in cancer cells." (PMID 29156771, 2017). "Furthermore, since Mcl-1 is highly expressed in several cancers, our results support the notion that the increased levels of Mcl-1 may block BOK pro-apoptotic activity by interacting and sequestering BOK away from localizing to the mitochondria." (PMID 29156771, 2017). "In addition, recent evidence shows that BOK is frequently deleted in cancers." (PMID 29156771, 2017). "Further, we found that the presence of BCL-B and its inhibition of BOK, can promote sublethal MOMP and thereby foster cancer cell invasiveness, relayed by EMT." (PMID 39996719, 2025). "Moreover, the observation of specific genomic regions of BOK being differentially represented in various cell lines underscores the dynamic nature of BOK gene expression and warrants further investigation to elucidate the functional significance of these variations in different cancer contexts." (PMID 37888203, 2023). "Amplification of the apoptotic inhibitors Bcl-2-like genes, MCL-1 and BCL-XL, and deletion of apoptotic-promoter genes BOK and PUMA are presented in the somatic copy number variations in over 3000 cancer specimens across 26 human cancer types." (PMID 34142021, 2021). "In those cancers, high BOK and low TRIM28 mRNA levels correlated with increased survival, and low BOK and high TRIM28 levels with decreased survival." (PMID 33043006, 2020). "Our results provide a plausible explanation for this finding, since apoptosis might be relayed more dominantly via BOK in LUAD, which further accentuates a tumor promoting role of BCL-B in this specific cancer biology." (PMID 39996719, 2025). "Likewise, aberrantly expressed miR-296-5p targets and downregulates BOK (apoptosis regulating gene), facilitates EMT, cancer invasion, and drug resistance." (PMID 35686109, 2022). "There are important implications of these findings for cancer biology, as colorectal cancer (CRC) cells may have a selective advantage from losing BOK expression." (PMID 33043006, 2020). "In a previous somatic copy-number alteration investigation involving 3131 cancer specimens, BOK was absent in numerous types of human cancer, indicating that BOK may exert a tumor-suppressing role in human cancers." (PMID 40806384, 2025). "Moreover, a high level of BOK expression was correlated with reduced survival and disease recurrence, which is not in agreement with previous findings in other cancers." (PMID 33291826, 2020). "So far, no reports show a role of BOK in cancers, but it will be very interesting to see whether BOK activity is dysregulated in certain types of cancers." (PMID 34766113, 2020).
tumor (16 papers, 2009 to 2025). "Specifically, loss of BOK reduced proliferation both in cell lines in vitro as well as in KrasG12D-driven tumor lesions in vivo." (PMID 35091677, 2022). "During tumor development in vivo, loss of BOK resulted in a lower tumor burden, with fewer, smaller, and less advanced tumors." (PMID 35091677, 2022). "BOK protein levels in tumours were also prognostic of clinical outcome but increased BOK protein levels surprisingly associated with earlier disease recurrence and reduced overall survival." (PMID 29374142, 2018). "Several genes were classified with function involved in DNA repair, apoptosis and tumor formation such as BOK which encodes a Bcl-2 related protein and PDE1B which may play a role in apoptosis." (PMID 19193219, 2009). "As such, its deletion should be an advantage in tumor survival and BOK should act as a tumor suppressor." (PMID 35091677, 2022). "Using an inducible model of Kras-driven murine lung cancer, we show that BOK plays a role in promoting tumor development, as Bok-proficient mice developed a larger number of more advanced lesions." (PMID 35091677, 2022). "Accordingly, patients receiving 5-FU therapy observed diminishing levels of BOK protein, suggesting a feedback mechanism triggered by tumor cells for survival." (PMID 34571731, 2021). "So far, only one study provided evidence for a potential role of BOK as a tumour suppressor in cancer, demonstrating that the Bok gene was silenced in many human cancers." (PMID 29374142, 2018). "We found that BOK protein levels were significantly reduced in tumour samples compared to their matched normal tissues (p = 0.0262, two-sided Wilcoxon signed-rank test)." (PMID 29374142, 2018). "Despite the exclusion of these potential outliers from the analysis, BOK protein levels still resulted in significantly decreased tumour compared to matched normal tissues (p = 0.0002, two-sided Wilcoxon signed-rank test)." (PMID 29374142, 2018). "In summary, this study highlights the ‘BAX/BAK-like’ protein BOK as a prognostic marker in CRC, with increased BOK tumour levels indicating unfavourable clinical outcome in Stage II/III CRC patients." (PMID 29374142, 2018). "In the colon of treated rats, the number of pre-neoplastic lesions and macroscopic tumours was lower than in the control group, while the number of apoptotic cells in the tumours and the expression of BOK (a pro-apoptotic gene) were higher in the treated group than in the control group." (PMID 38794302, 2024). "By sequestering miRNAs involved in reproductive cancers, BOK circRNAs might play critical roles in altering the expression levels of tumor-promoting and tumor-suppressing genes that are relevant to these malignancies." (PMID 37888203, 2023). "Using KrasG12D/+Bok−/− mice, we observed an overall tumor-promoting function of BOK in vivo." (PMID 35091677, 2022). "However, the peak region of the genomic deletion in question contains 18 other genes and hard evidence that BOK is indeed a tumor suppressor is currently missing." (PMID 33043006, 2020). "Given the evidence for a proapoptotic role of BOK, this finding could hint toward a tumor suppressor–like activity of BOK." (PMID 33043006, 2020). "This may be attributed to the existence of different roles of BOK in tumor establishment and recurrence, probably because of its involvements in different cell regulation processes apart from apoptosis." (PMID 33291826, 2020). "Indeed, we did not observe a direct correlation of cleaved caspase-3 levels and BOK protein levels in the CRC tumour samples." (PMID 29374142, 2018). "This apparent discrepancy may reflect the contributions of different activities of BOK during tumour establishment vs recurrence and metastasis." (PMID 29374142, 2018). "Interestingly, BOK protein levels were increased in tumour samples from colorectal patients with unfavourable outcome compared to favourable outcome (Mann–Whitney U test, p = 0.0192)." (PMID 29374142, 2018).
tumor (continued). "Interestingly, the same study indicated that BOK may exert a tumor-suppressor-like function at later stages of disease." (PMID 35091677, 2022). "Hence, these data do support a tumor-suppressing action of BOK and suggest that BOK protein levels may be useful as a prognostic marker in late-stage NCSLC patients." (PMID 33043006, 2020). "However, the role of BOK in regulating tumor initiation and progression remains unclear." (PMID 40806384, 2025). "In their studies, Srivastava and colleagues (2019) had reported BOK to be a positive regulator of uridine monophosphate synthase (UMPS) in the metabolism of 5-FU, and that BOK inhibition had resulted in decreased tumor cell sensitivity towards 5-FU treatment." (PMID 34571731, 2021). "Interestingly, deletion of BOK inhibited the ER-stress response and induction of pro-apoptotic BH3-only proteins BIM and PUMA, placing BOK's tumour promoting role upstream of MOMP." (PMID 29769323, 2018). "Further analysis identified a lack of correlation between tumour levels of BOK and ER stress markers, GRP78 and GRP94." (PMID 29374142, 2018). "Taken together, these data show that BOK impacts on proliferation as well as on DNA damage repair response, which could explain the decreased tumor burden observed in the absence of BOK." (PMID 35091677, 2022). "Interestingly, the tumour suppressive effect of BOK in NSCLC does not seem to be through apoptotic regulation and is instead through antagonism of TGF-β2 mediated epithelial to mesenchymal transition (EMT) and cell migration." (PMID 29769323, 2018). "Thus we next evaluated the expression levels of BOK protein and the key ER stress markers 78 kDa glucose-regulated protein/binding immunoglobulin protein (GRP78), heat shock protein 90 kDa beta member 1 (GRP94) and Calreticulin in fresh-frozen tumour resections of CRC patients." (PMID 29374142, 2018). "BCL2-related ovarian killer (BOK) is a non-canonical member of the BCL2 family and serves as a tumor suppressor by triggering cell death." (PMID 33799952, 2021).
infection (2 papers, 2014 to 2021). The state of being infected such as from the introduction of a foreign agent such as serum, vaccine, antigenic substance or organism. "These single-mutant cells all exhibited a similar pattern of infection with either virus comparable to WT settings, demonstrating that, individually, BID, BIM, PUMA, or BOK are dispensable for suppression of ∆vMIA/vIBO-driven, BAX/BAK-mediated PCD." (PMID 34578288, 2021). "Given the recognized crucial functions of BID, BIM, PUMA, and BOK in activating BAX/BAK-dependent cell death, we assessed viability and viral titer in WT compared to Bid−/−Bim−/−Puma−/− as well as Bid−/−, Bim−/−, Puma−/−, and Bok−/− BMDM during infection with K!81 or ∆M38.5/M41.1 viruses." (PMID 34578288, 2021).
movement disorder (1 paper, 2025). Neurological conditions resulting in abnormal voluntary or involuntary movement, which may impact the speed, fluency, quality and ease of movement. "BOK (Importance 15.2), a pro-apoptotic gene, was linked to Haloperidol Decanoate (PUBCHEM_CID: 52919), targeting programmed cell death in movement disorders." (PMID 40864790, 2025).
BOK also shares sentences with these, for which no sentence is quoted: adenocarcinoma (1 paper); Atrophy (1); B cell lymphoma (1); necrotizing vasculitis (1); neurological disorders (1); omphalocele (1); sarcopenia (1); squamous cell carcinoma (1).